SIRT1 (sirtuin 1)
Diseases named in the same sentence as SIRT1 in open-access papers (continued):
Sharing a sentence is not in itself a finding about the gene and the disease.
Nephropathy (54 papers, 2011 to 2025). A nonspecific term referring to disease or damage of the kidneys. "Experimental evidence indicates that SIRT1 is pivotal in mediating age-associated pathological alterations, including kidney damage related to aging." (PMID 39911234, 2024). "Our results showed that Nur77 deficiency markedly aggravated aging‐related nephropathy and elucidated a key role for Nur77 in the stabilization of Sirt1 homeostasis during renal aging." (PMID 36883265, 2023). "Evidence suggests that renal and systemic klotho and sirtuin 1 (SIRT1) deficiencies worsen kidney damage induced by exogenous stresses." (PMID 32942691, 2020). "Activating Sirt1 or Nur77 helped improve Nur77 deficiency‐aggravated aging nephropathy." (PMID 36883265, 2023). "To identify whether Nur77 deficiency–mediated Sirt1 degradation was the key process in aging nephropathy, we treated aged WT and Nr4a1−/−mice with the activator, resveratrol (Res)." (PMID 36883265, 2023). "Our preclinical data suggest that targeted Sirt1 agonism represents a promising therapeutic intervention for progressive crystallopathic nephropathy, potentially disrupting the inflammation–crystallisation vicious cycle." (PMID 40824734, 2025). "This study repurposes ROSU in modulating radiation-induced nephropathy, revealing its novel role in redirecting cell fate from apoptosis toward mitophagy through SIRT1/FOXO3a activation." (PMID 41460314, 2025). "Previous research has shown that increasing SIRT1 expression restores cellular oxidant-antioxidant equilibrium and reduces kidney damage in mouse models of acute renal injury." (PMID 40006061, 2025). "Our previous research showed that Sirt1 promotes M2Mφ to alleviate crystal‐induced kidney damage, and the transformation of this phenotype is essentially driven by metabolic reprogramming." (PMID 40824734, 2025). "In contrast induced nephropathy (CIN), SIRT1 activated by calorie restriction was able to reduce kidney damage via the modulation GPX4." (PMID 40109363, 2025). "SIRT1 expression has been identified as a contributing factor in the development of chronic renal allograft dysfunction and chronic cyclosporine A (CsA) nephropathy." (PMID 39911234, 2024). "Very interestingly, this protein is known to exert a protective role against oxidative stress and to attenuate nephropathy progression in diabetic mice and possibly in human kidneys via stimulation of Sirtuin-1 expression." (PMID 36769128, 2023). "In this regard, ellagic acid (EA) was shown to protect against iron-induced kidney damage in rats by activation of SIRT1." (PMID 35241966, 2022). "Lastly, studies have reported that SIRT1-mediated autophagy not only play a role in endocrine disorders but also other diseases such as neurodegeneration and nephropathy." (PMID 35909524, 2022). "NF-ĸB is involved in the development of oxidative stress as well as inflammation and can exacerbate kidney damage; Sirt1 activation deacetylates the NF-ĸB p65 subunit." (PMID 34439446, 2021). "Taken together, TF exhibits a strong nephroprotective ability to suppress CaOx-induced kidney damage through the recovery of the antioxidant defense system regulated by miR-128-3p/SIRT1 axis." (PMID 33867828, 2021). "In a nephropathy model, systemic SIRT1 activation suppresses intestinal/renal TNFα expression and ameliorates renal dysfunction." (PMID 33513830, 2021). "Nonetheless, future studies should be directed to ascertain this particular role of miR-200a and SIRT1 and the mechanisms responsible for this interaction in kidney damage." (PMID 32887498, 2020). "The results provide corroborative evidence as to the significance of SIRT1 signalling in the regulation of renal lipotoxicity and nephropathy due to maternal obesity." (PMID 30641941, 2019).
Nephropathy (continued). "The inverse correlation between SIRT1 and albuminuria reported in this study reflects findings from human and experimental research that indicate an early drop in tubular SIRT1 prior to the onset of nephropathy, underscoring its essential function in preserving renal metabolic health." (PMID 41470091, 2025). "Curcumin, a polyphenolic compound derived from turmeric, modulates oxidative stress and mitigates mitochondrial injury, thereby delaying the initiation and progression of aristolochic acid-induced nephropathy through the activation of the SIRT1/Nrf2/HO-1 signaling cascade." (PMID 39911234, 2024). "In addition, we confirmed the compelling role of Nur77 in protecting against aging nephropathy via Sirt1." (PMID 36883265, 2023). "Based on these recent results, there is a slight possibility that NMN, which has been shown to be safe and effective in humans, may inhibit the progression of renal damage by activating Sirt1 in the early stages of nephropathy." (PMID 34439446, 2021). "In this respect, a selective SIRT1 inhibitor EX-527, showed its inhibitory activity against fibroblast activation markers, which reflects the importance of EX-527 in the development process of antidiabetic nephropathy drugs." (PMID 32365537, 2020). "However, additional studies are necessary to further explore the mechanisms by which SIRT1 activation antagonizes cisplatin‐induced kidney damage." (PMID 32881246, 2020). "Our study suggests that deacetylation of HIF‐1α induced by Sirt1 activation may have a therapeutic benefit to slow kidney damage in the aging process." (PMID 30614190, 2019). "Additionally, a notable decrease in Sirt1 protein was observed in nephropathy mice induced by Gly." (PMID 40824734, 2025). "Rosmarinic acid and resveratrol attenuate cardiac dysfunction through SIRT1-mediated PGC-1α deacetylation, while Astragalus-derived astragaloside IV enhances mitogenesis via SIRT1/PGC1α/NRF1 and stabilizes mitochondrial dynamics in nephropathy." (PMID 40866350, 2025). "Resveratrol, with the property of reducing oxidative stress-mediated renal injury in the animal model of nephropathy, can inhibit PTH induced apoptosis and restore bcl-2 expression as a sirtuin 1 agonist." (PMID 35166167, 2022). "In the presence of EX527, a specific SIRT1 antagonist, the CR-mediated protection on CIN was lost, confirming that CR-mediated protection from contrast-induced nephropathy occurs via SIRT1 activation." (PMID 34712381, 2021). "In conclusion, Sirt1 enhances the resistance of renal tubular epithelium to ferroptosis induced by CaOx crystals through the PGC‐1α/NRF2/GPX4 pathway, thereby reducing CaOx‐induced kidney damage and further crystal deposition." (PMID 39498889, 2024). "Thus, we sought to investigate the relationship between SIRT1 and claudin 1 in human kidney biopsies, in an experimental adriamycin (ADR)-induced nephropathy model, and in immortalized mouse podocytes." (PMID 38114708, 2023). "Increasing the total level and nuclear activity of SIRT1 could reduce the expression of caspase-3 and Bax and increase SOD and GSH levels in doxorubicin-induced nephropathy." (PMID 34845191, 2021). "Additionally, using SIRT1 and SIRT-3 knock out male mice may be needed to detect whether the observed exacerbated kidney damage in CS-exposed MI male mice is due to decreased SIRT-1 and SIRT-3 levels, consequently potential enhanced mitochondria dysfunction." (PMID 32519752, 2020). "Sirtuin-1 (Sirt-1), a histone deacetylase, was found to be overexpressed in lupus-prone mice, MRL/lpr mice, and the down-regulation of Sirt-1 resulted in short-term enhanced H3 and H4 acetylation, with reduced levels of anti-dsDNA, glomerular IgG deposition and kidney damage." (PMID 25988383, 2015). "Overall, our findings do not entirely refute the role of the SIRT1 and SIRT2 pathways in DN disorders, but offer insights into the pathophysiological roles of SIRT1 and SIRT2 in nephropathy." (PMID 36139886, 2022).
injury (53 papers, 2015 to 2025). Damage inflicted on the body as the direct or indirect result of an external force, with or without disruption of structural continuity. "Our study reveals that a decline in SIRT1 within spinal CaMKIIα+ neurons is associated with the development of pain subsequent to nerve injury, involving the Nav1.3 sodium channel." (PMID 38828629, 2024). "In summary, the results of the present study indicate that Nim has a potential therapeutic effect on APAP‐induced acute liver injury, which can be attributed to its ability to target SIRT1." (PMID 40375435, 2025). "Consistent with the WB results, Cga also reversed the reduction in the mRNA expression of Sirt1 in PA-induced liver injury." (PMID 40069808, 2025). "The beneficial effects of TGS on cardiomyocytes and neurons are ascribed to its ability to activate SIRT1 to promote mitochondrial biosynthesis through the SIRT1/PGC1α axis and prevent brain injury and ischemic heart." (PMID 36900446, 2023). "In a neonatal brain injury model, SIRT1 inhibition promoted OPC differentiation and neuroregeneration." (PMID 36136587, 2022). "A decreased SIRT1 expression level has been observed in IPF, and the activation of Sirt1 expression by Sirt1 activator reduces lung fibrosis in the bleomycin-induced lung injury mouse model." (PMID 34207528, 2021). "These potentially positive effects of NR on Sirt1 and Tfam expressions need to be looked for in a different, less devastating model of kidney injury than the present IRI model." (PMID 34061900, 2021). "Icariin-induced protective effects against intestinal I/R-induced acute lung injury are mediated through the SIRT1/FOXO3 signaling pathway." (PMID 34630849, 2021). "Consistent with this study, resveratrol reduced ROS production and NLRP3 activation in a SIRT1-dependent traumatic brain injury rat model." (PMID 34676022, 2021). "A previous study demonstrated that SIRT1 participated in the anti-inflammatory activity in lipopolysaccharide-induced acute lung injury." (PMID 32695008, 2020). "In the present study, we reported that the expression of Sirt1 was downregulated after brain injury in vivo; a similar result was obtained in primary astrocytes after stimulation with IL-1β in vitro." (PMID 28356158, 2017). "Further evidence demonstrates that SIRT1 overexpression can also play a protective role in a variety of in vivo and in vitro models of nerve injury." (PMID 29081884, 2017). "It is also possible that SIRT1 activity, rather than circulating levels, plays a more critical role in mediating age-dependent susceptibility to kidney injury, a distinction not captured by ELISA-based quantification." (PMID 40507714, 2025). "Moreover, numerous researchers have investigated the effects of SIRT1 activation in animal models of brain injury." (PMID 39619997, 2024). "Sirtuin-1 (SIRT-1) is an NAD+-dependent deacetylase that acts as a transcription factor for many different physiological processes, is implicated in alcohol-induced liver injury, and is overexpressed in human HCC." (PMID 39335475, 2024). "Therefore, it would be difficult to obtain our expected results, that the inhibition of Sirt1 by its inhibitor eliminated ERS-mediated protection against APAP-induced liver injury in vivo." (PMID 37959727, 2023). "Similarly, GDF15, another member of the GDF family, can upregulate SIRT1 expression in lipopolysaccharide-induced acute lung injury." (PMID 34262905, 2021). "In the light of the protective effects of SIRT1 in kidney, daidzein administration could ameliorate I/R-induced kidney injury by stimulating the expression and activity of SIRT1." (PMID 28425936, 2017). "It remains unclear whether Cga directly activates SIRT1 in the context of PA-induced liver injury." (PMID 40069808, 2025). "Hence, drugs target SIRT1 is believed to a novel therapeutic in patients with acute lung injury." (PMID 35341153, 2022).
injury (continued). "Thus, Sirt1 plays a protective role against astrocyte activation, which may be associated with the regulation of the MAPK pathway activation induced by brain injury in vitro and in vivo." (PMID 28356158, 2017). "The protective effects of SIRT1, SIRT3, and SIRT5 against cisplatin-induced kidney injury have been reported." (PMID 38034992, 2023). "SIRT1 has been reported to rescue oxidative stress and inflammation in several pathologies, including APAP-induced liver injury." (PMID 37107244, 2023). "We also found that Sirtinol, a pharmacological inhibitor of SIRT1, abolished the protection of RSV against NMDA-mediated nerve injury, indicating that the neuroprotective role of RSV is possibly achieved by activation of SIRT1." (PMID 29081884, 2017). "Therefore, we analyzed the relationship between the SIRT1-mediated BDNF–TrkB signaling pathway and fluorosis brain injury, learning and memory, and provide new ideas and a theoretical basis for preventing and treating fluorosis brain injury." (PMID 37711250, 2023). "Therefore, selective inhibition of SIRT1 by EX-527 might improve endotoxemia-related acute lung injury moderately via inhibition of mTOR, which suggests that selective SIRT1 inhibitors may have potential for the pharmacological treatment of inflammatory lung injury." (PMID 32365537, 2020). "Furthermore, melatonin reverses the impairment of autophagy by regulating SIRT1 expression, thereby imparting a protective effect against FD/CIH-induced liver injury." (PMID 30411173, 2019). "Sirtuin 1 (SIRT1) and SIRT3 play protective roles against cisplatin-induced kidney injury." (PMID 29651144, 2018). "By restoring SIRT1 activity, pyridostigmine may enhance antioxidant defenses, reduce inflammatory responses, and prevent hepatocyte apoptosis, thereby contributing to its hepatoprotective effects against MTX-induced liver injury." (PMID 40564221, 2025).
neuroblastoma (50 papers, 2008 to 2025). Neuroblastoma (NB) is the most common solid, extracranial childhood tumor. "We utilized iterative medicinal chemistry to identify an analog, DDL-214, of our original SirT1-enhancing hit A0322 that increased SirT1 protein levels in ApoE4-expressing N2a (N2a-E4) murine neuroblastoma cells." (PMID 40269061, 2025). "A previous study showed that RSV treatment significantly increased both SIRT1 protein expression and SIRT1 activity and inhibited PrP106–126-induced cell death in neuroblastoma cells." (PMID 39273653, 2024). "CERKL alleviated neuronal damage through activating mitophagy in a SIRT1/PINK1/Parkin-dependent pathway in human neuroblastoma cells." (PMID 36507335, 2022). "Taken together, we have shown for the first time that SRT1720, as a SIRT1 activator, can prevent PQ-induced cytotoxicity in human neuroblastoma SH-SY5Y cells." (PMID 36379180, 2022). "EGb 761 protects against β-amyloid-induced neurotoxicity in the N2a neuroblastoma cell line through SIRT1 activation." (PMID 36432638, 2022). "The relationship between MIAT, SIRT1, and miR-29b in neuroblastoma cell lines was studied in young and aged C57BL/6 mice." (PMID 35990888, 2022). "NaF-induced suppression of Sirt1 has also reportedly occurred in the testes of golden hamsters, F9 cells, and human neuroblastoma SH-SY5Y cells." (PMID 36186127, 2022). "We used the SK-N-SH neuroblastoma cells to study the role of Sirt-1 expression on physiological roles in neuronal cells." (PMID 33834065, 2021). "Recently, we showed that 1 μM 24-OHC up-regulates both expression and synthesis of the neuroprotective enzyme sirtuin 1 (SIRT1) in neuroblastoma SK-N-BE cells, consequently preventing the intracellular accumulation of insoluble tau aggregates in neurons." (PMID 34067119, 2021). "SK-N-SH neuroblastoma cells were employed to figure out the roles of Sirt-1 expression on physiological roles in neuronal cells." (PMID 33834065, 2021). "Our data demonstrate that DOX-induced apoptosis was enhanced by deficiency of SIRT1 and AROS and increased by GSK3β expression in human neuroblastoma SH-SY5Y cells." (PMID 32158616, 2020). "Recent studies have shown that suppression of deacetylase activity or expression of SIRT1 induces apoptosis in human neuroblastoma cells." (PMID 32158616, 2020). "The increase of SIRT1 levels in neuroblastoma cells incubated with 24-OH was further confirmed by immunocytochemistry after 3 h cell treatment; this effect was completely prevented by the administration of the ROS inhibitors, either of apocynin or rotenone." (PMID 29883958, 2018). "A beneficial effect of 24-OH was demonstrated in SK-N-BE neuroblastoma cells, and is due to its ability to modulate the deacetylase sirtuin 1 (SIRT1), which contributes to preventing the neurotoxic accumulation of the hyperphosphorylated tau protein." (PMID 29883958, 2018). "Murine neuroblastoma N2a cells stably transfected with ApoE4 (N2a-E4) show significantly lower levels of SirT1 as compared to cells transfected with ApoE3, and therefore N2a-E4 cells were adopted for use in HTS." (PMID 30514854, 2018). "Resveratrol protected human neuroblastoma SK-N-BE cells from the toxicity induced by expression of α-syn A30P mutant form by a SIRT1-dependent mechanism as revealed by data obtained with sirtinol, a specific inhibitor of SIRT1." (PMID 25946078, 2015). "Although there are convincing studies that argue for a tumour suppressive role of Sirt1, recent data provide functional evidence that Sirt1 has oncogenic properties in neuroblastomas by facilitating n-myc stabilization." (PMID 24088390, 2013). "Our data identify SIRT1 as an important co-factor for N-Myc oncogenesis and provide important evidence for the potential application of SIRT1 inhibitors in the prevention and therapy of N-Myc–induced neuroblastoma." (PMID 21698133, 2011). "The data confirmed the major role of SIRT1 in the initiation of N-Myc-induced neuroblastoma in vivo." (PMID 21698133, 2011).